ARHGAP26 (Rho GTPase activating protein 26)
Description:
GTPase-activating protein for RHOA and CDC42. Facilitates mitochondrial quality control by promoting Parkin-mediated recruitment of autophagosomes to damaged mitochondria. Negatively regulates the growth of human parainfluenza virus type 2 by inhibiting hPIV-2-mediated RHOA activation via interaction with two of its viral proteins P and V. [Isoform 2]: Associates with MICAL1 on the endosomal membrane to promote Rab8-Rab10-dependent tubule extension. After dissociation of MICAL1, recruits WDR44 which connects the endoplasmic reticulum (ER) with the endosomal tubule, thereby participating in the export of a subset of neosynthesized proteins.
Synonyms: GRAF1; GRAF; KIAA0621; OPHN1L; OPHN1L1
Tractability: Antibody: UniProt places it where antibodies can reach, with high confidence. PROTAC: ubiquitination databases record sites on it; its protein half-life has been measured.
Gene: Protein-coding gene on chromosome 5 (142,770,377 to 143,229,011, forward strand). Ensembl gene ENSG00000145819.
Subcellular location: Endosome membrane (Isoform 2); Cytoplasm; Cell junction, focal adhesion; Cytoplasm, cytoskeleton
Subcellular location (Human Protein Atlas): Cytosol
Pathways (Reactome):
Signal Transduction: CDC42 GTPase cycle; RAC1 GTPase cycle; RAC2 GTPase cycle; RAC3 GTPase cycle; RHOA GTPase cycle; RHOB GTPase cycle; RHOC GTPase cycle; RHOD GTPase cycle; RHOJ GTPase cycle; RHOQ GTPase cycle
Gene Ontology:
Molecular function: phospholipid binding; protein binding; protein-macromolecule adaptor activity; GTPase activator activity
Biological process: mitophagy; actin cytoskeleton organization; regulation of small GTPase mediated signal transduction; signal transduction
Cellular component: cytoplasm; cytosol; endosome membrane; mitochondrion; cytoskeleton; focal adhesion
Genetic constraint (gnomAD): Loss-of-function variants: 30 observed, 82.49 expected, observed/expected ratio (o/e) 0.36, 90% interval 0.27 to 0.49. The upper end of that interval is the gene's LOEUF score, 0.49, which puts it in group 2 of 6, group 1 being the genes least tolerant of losing a copy. Missense variants: 606 observed, 841.65 expected, observed/expected ratio (o/e) 0.72, 90% interval 0.67 to 0.77. Synonymous variants: 298 observed, 297.01 expected, observed/expected ratio (o/e) 1, 90% interval 0.91 to 1.1.
Cancer hallmarks: invasion and metastasis (promotes); invasion and metastasis (suppresses); suppression of growth (promotes); proliferative signalling (promotes)
Homologues: Orthologues: chimpanzee ARHGAP26 (99% identical), macaque ARHGAP26 (99% identical), guinea pig ARHGAP26 (98% identical), dog ARHGAP26 (98% identical), rat Arhgap26 (98% identical), mouse Arhgap26 (97% identical), rabbit ARHGAP26 (97% identical), pig ARHGAP26 (96% identical), tropical clawed frog arhgap26 (85% identical). Paralogues in human: ARHGAP10 (59% identical), ARHGAP42 (56% identical), OPHN1 (47% identical).
Diseases named in the same sentence as ARHGAP26 in open-access papers:
ARHGAP26 is named in the same sentence as 63 diseases in open-access papers, as found by Europe PMC text mining. Sharing a sentence is not in itself a finding about the gene and the disease. The quoted sentences say what the papers report.
gastric cancer (18 papers, 2016 to 2024). A primary or metastatic malignant neoplasm involving the stomach. "Meanwhile, more investigations are warranted to explore the underlying mechanism through which circ-ARHGAP26 affects tumorigenesis and progression of gastric cancer." (PMID 34716859, 2022). "ARHGAP26 disruption induced a dramatic loss of an epithelial cellular phenotype and increased gastric cancer cell invasion and migration." (PMID 31004081, 2019). "The presence of the CLDN18-ARHGAP26 mutation has been shown to facilitate the progression and metastasis of gastric cancer (GC) through the loss of CLDN18 function and the acquisition of ARHGAP26 functions." (PMID 38704377, 2024). "In gastric cancer, the fusion of ARHGAP26 and the claudin-18 gene (CLDN18) led to the translation of an abnormal fusion protein, which promoted the development of gastric cancer." (PMID 37175461, 2023). "In functional experiments, downregulation of circ-ARHGAP26 resulted in a decline in the proliferation of gastric cancer epithelial cells and an increase in apoptosis." (PMID 34716859, 2022). "Second, downstream mechanisms responsible for the abnormal expression of ARHGAP26 in tumors still need to be further investigated, including the expression of circ-ARHGAP26 in gastric cancer patients." (PMID 34716859, 2022). "The expression of circ-ARHGAP26 was also lower in five gastric cancer cell lines (AGS, BGC-823, HGC-27, MGC-803, and SGC-7901) than that in the normal gastric epithelial GES-1 cell line." (PMID 34716859, 2022). "Among 20 cancers of unknown primary examined, two had the CLDN18:ARHGAP26 fusion, which has been reported in gastric carcinomas and may suggest the origin of the unknown primary tumor." (PMID 38800398, 2024). "In gastric cancer, ARHGAP26 is fused with claudin-18 gene (CLDN18), and the translated abnormal fusion protein regulates the development of gastric cancer, while circular RNA ARHGAP26 (circ-ARHGAP26) modulates microRNA through a “sponge” mechanism to affect the progression of gastric cancer." (PMID 34716859, 2022). "In addition, the expression of circ-ARHGAP26 in gastric tissues of patients with mild and moderate gastritis was also significantly lower than that of the normal gastric tissues, but higher than that of gastric cancer tissues." (PMID 34716859, 2022). "GRAF1 (also named ARHGAP26) was reported to be a tumor suppressor that was functionally or genetically inactivated in several tumors, including gastric cancer, ovarian cancer, and metastatic brain cancer." (PMID 36849460, 2023). "In 2014, the fusion of ARHGAP26 and CLDN18 (CLDN18-ARHGAP26 fusion) was first reported in gastric cancer patients." (PMID 34716859, 2022).
myelodysplastic syndrome (7 papers, 2006 to 2022). A clonal hematopoietic disorder characterized by dysplasia and ineffective hematopoiesis in one or more of the hematopoietic cell lines. "However, mutations of ARHGAP26 are a rare cause of juvenile myelomonocytic leukemia, one of the most common pediatric myelodysplastic syndromes." (PMID 20226058, 2010). "Abnormal methylation of the ARHGAP26 promoter and downregulation of the ARHGAP26 mRNA was observed in acute myeloid leukemia and myelodysplastic syndrome." (PMID 24886876, 2014).
ovarian carcinoma (6 papers, 2013 to 2023). A malignant neoplasm originating from the surface ovarian epithelium. "In this study, low ARHGAP26 expression was observed in ovarian cancer tissues and was associated with a poor overall survival and higher β-catenin expression in patients with ovarian cancer." (PMID 31004081, 2019). "Herein, the present study assessed ARHGAP26 expression and its underlying mechanism in regulation of ovarian cancer cell proliferation, invasion, and migration." (PMID 31004081, 2019). "A previous study showed that expression of ARHGAP26 in ovarian cancer tissues was significantly reduced and related to poor prognosis of the patients." (PMID 34716859, 2022). "Animal experiments have shown that upregulation of ARHGAP26 reduces the lung metastasis of ovarian cancer cells." (PMID 34716859, 2022). "Smurf1 also leads to the invasion and metastasis by the interaction and ubiquitination of Rho GTPase-activating protein 26 (ARHGAP26) in ovarian cancer cells." (PMID 33114139, 2020). "ARHGAP26 overexpression inhibits the proliferation, migration, and invasion of ovarian cancer cells." (PMID 31004081, 2019). "The correlation between ARHGAP26 expression and the prognosis of patients with ovarian cancer was analyzed with a log-rank (Mantel–Cox) test." (PMID 31004081, 2019). "ARHGAP26 overexpression inhibited ovarian cancer cell proliferation, migration, and invasion, and lung metastasis in xenograft nude mice bearing ovarian cancer, whereas ARHGAP26 silencing promoted these behaviors." (PMID 31004081, 2019). "Decreased ARHGAP26 expression was observed in ovarian cancer cell lines compared with that in IOSE80 cells, with the two lowest expression levels detected in A2780 and HEY cells, and the highest expression detected in SKOV3 cells." (PMID 31004081, 2019). "We analyzed the mRNA expression levels of β-catenin and SMURF1 in ovarian cancer tissues and performed a Pearson’s correlation analysis between ARHGAP26 and β-catenin or SMURF1 and β-catenin." (PMID 31004081, 2019). "SMURF1 upregulation promoted ubiquitination of ARHGAP26 and induced ovarian cancer cell migration and invasion, which were inhibited by ARHGAP26 upregulation." (PMID 31004081, 2019). "ARHGAP26 mRNA expression was negatively correlated with the mRNA expression of β-catenin in ovarian cancer tissues, whereas SMURF1 mRNA expression was positively correlated with the mRNA expression of β-catenin in ovarian cancer tissues." (PMID 31004081, 2019). "In conclusion, the present study preliminarily provides insights into the anticancer effect of ARHGAP26 in ovarian cancer cells." (PMID 31004081, 2019). "ARHGAP26 downregulation promoted ovarian cancer cell invasion and migration by activating the β-catenin pathway." (PMID 31004081, 2019). "Here we demonstrated a similar role of ARHGAP26 in regulation of cell proliferation, invasion, and migration in ovarian cancer." (PMID 31004081, 2019). "Here, the involvement of ARHGAP26 in ovarian cancer cell proliferation and migration was investigated." (PMID 31004081, 2019). "We analyzed the expression levels of ARHGAP26 in ovarian cancer tissues using TCGA and our independent hospital databases." (PMID 31004081, 2019). "ARHGAP26 upregulation inhibited ovarian cancer cell proliferation, invasion, and migration in vitro and lung metastasis in vivo." (PMID 31004081, 2019). "Occurrence of ARHGAP26 antibody-positive ACA led to the diagnosis of ovarian carcinoma in one of the patients reported here, suggesting a possible paraneoplastic aetiology of the condition." (PMID 23320754, 2013). "Thus, researchers believe that SMURF1-dependent regulation of ARHGAP26 ubiquitination promotes the invasion and migration of ovarian cancer cells through the β-catenin pathway." (PMID 34716859, 2022).
ovarian carcinoma (continued). "For example, ARHGAP26 expression is significantly reduced in acute myeloid leukemia (AML), chronic myeloid leukemia (CML), and ovarian cancer, while the transcription factor activity of ARHGAP26 is significantly increased and expression of ARHGAP26 is upregulated in prostate cancer." (PMID 34716859, 2022). "Interestingly, upregulation of ARHGAP26 in SKOV3 ovarian carcinoma cells was shown to effectively inhibit the migration and invasion of tumor cells due to the upregulation of smad ubiquitination regulatory factor 1 (SMURF1)." (PMID 34716859, 2022). "Nevertheless, the cellular function of SMURF1 and its role in regulation of ARHGAP26 in ovarian cancer remain largely unknown." (PMID 31004081, 2019). "Therefore, we came to the conclusion that ARHGAP26 is of great importance in the tumorigenesis of ovarian cancer." (PMID 31004081, 2019). "However, the molecule mechanism and regulation of ARHGAP26 in ovarian cancer tumorigenesis is still unclear." (PMID 31004081, 2019). "Overall, SMURF1-mediated ubiquitination of ARHGAP26 may promote invasion and migration of ovarian cancer cells via the β-catenin pathway." (PMID 31004081, 2019). "Moreover, β-catenin mRNA expression was found to be increased in ovarian cancer tissues and negatively correlated with ARHGAP26 mRNA expression." (PMID 31004081, 2019). "Hongping Li at Shenzhen Children’s Hospital, Yuanfang Zhu at Bao’an Maternity and Child Health Hospital, and co-workers showed that low levels of a tumor-suppressing protein, Rho GTPase-activating protein 26 (ARHGAP26), promote the invasion and migration of ovarian cancer cells." (PMID 31004081, 2019). "SMURF1-mediated ubiquitination of ARHGAP26 may promote ovarian cancer cell invasion and migration through the β-catenin signaling pathway." (PMID 31004081, 2019). "Whether ARHGAP26 can be regulated in ovarian cancer remains an unanswered question." (PMID 31004081, 2019). "ARHGAP26 overexpression inhibited SMURF1-mediated cell migration, invasion, and β-catenin signaling in ovarian cancer, thereby suggesting that SMURF1-mediated ARHGAP26 ubiquitination may promote ovarian cancer cell invasion and migration via the β-catenin signaling pathway." (PMID 31004081, 2019). "Moreover, the finding of ovarian cancer in one of our patients suggests that anti-Ca/anti-ARHGAP26-positive ACA might be of paraneoplastic aetiology in some cases." (PMID 23320754, 2013). "In this study, we report that ARHGAP26 is downregulated, whereas β-catenin and SMURF1 are upregulated in ovarian cancer patients." (PMID 31004081, 2019). "Therefore, ARHGAP26 may be a promising novel therapeutic target for ovarian cancer treatment." (PMID 31004081, 2019). "The results demonstrated downregulated ARHGAP26 mRNA expression in ovarian cancer tissues compared with adjacent noncancerous ovarian tissues from TCGA and independent hospital cohorts." (PMID 31004081, 2019). "Our results provided evidence, suggesting that ARHGAP26 inhibits ovarian cancer cell invasion and migration in vivo and in vitro, and SMURF1-mediated ARHGAP26 ubiquitination may promote ovarian cancer cell invasion and migration via the β-catenin signaling pathway." (PMID 31004081, 2019). "It is of note in this context that ARHGAP26 has been shown to be expressed in a subset of ovarian cancer tissues, partly at high levels, while it is absent or present only at low levels in normal ovarian tissue; however, no tumour tissue from patient 1 was available for analysis in this study." (PMID 23320754, 2013). "Additionally, Chen at al. studied Rho GTPase-activating protein 26 (ARHGAP26), a negative regulator of the Rho family, in a cohort of 85 ovarian cancer tissues and corresponding non-malignant regions." (PMID 32443784, 2020).
cerebellar ataxia (4 papers, 2010 to 2023). A neurological syndrome characterized by clumsy and uncoordinated movement of the limbs, trunk, and cranial muscles. "Cognitive impairment has been associated with such anti-ARHGAP26 autoantibodies and is mainly detected in diseases entailing cerebellar ataxia associated with immunopathology in cerebellar structures." (PMID 39081998, 2023). "In summary, ARHGAP26 autoantibodies were primarily reported in patients with cerebellar ataxia, but have also been associated with additional clinical features such as psychotic symptoms, depression, and cognitive decline." (PMID 30158896, 2018). "In an additional case, ARHGAP26 antibodies were not only associated with cerebellar ataxia, but also with cognitive and affective symptoms, indicating a broader clinical spectrum." (PMID 30158896, 2018). "Our findings indicate a role of autoimmunity to ARHGAP26 in the pathogenesis of subacute inflammatory cerebellar ataxia and expand the panel of diagnostic markers for this devastating condition." (PMID 20226058, 2010). "Our findings suggest a role of autoimmunity against ARHGAP26 in the pathogenesis of subacute inflammatory cerebellar ataxia, and extend the panel of diagnostic markers for this devastating disease." (PMID 20226058, 2010). "Further research is now needed to evaluate the exact role of anti-ARHGAP26 antibodies in the pathogenesis of cerebellar ataxia, involving the development of a passive transfer animal model." (PMID 20226058, 2010). "Two more patients with ARHGAP26 autoantibodies and cerebellar ataxia were reported 3 years later." (PMID 30158896, 2018).
Cognitive impairment (4 papers, 2018 to 2023). Abnormal cognition is characterized by deficits in thinking, reasoning, or remembering. "Here, we report three new cases with predominant cognitive impairment and associated malignancy, further extending the clinical spectrum associated with ARHGAP26 autoantibodies and strengthening their potential paraneoplastic context." (PMID 30158896, 2018). "In summary, we here describe three new cases with ARHGAP26 autoantibodies with tumor association that presented with predominant cognitive impairment." (PMID 30158896, 2018). "In addition, anti-ARHGAP26 autoantibodies associated with isolated cognitive impairment have also been reported to be associated with tumors." (PMID 39081998, 2023). "The frequent reports of cognitive impairment associated with anti-ARHGAP26 autoantibodies suggest that anti-ARHGAP26 autoantibodies may reflect additional neuroinflammation that is not part of DLB or is secondary to neurodegeneration." (PMID 39081998, 2023). "We here describe three new ARHGAP26-positive cases with isolated cognitive impairment in two patients and a tumor association in all three cases, suggesting a broader clinical spectrum and highlighting the importance to screen antibody-positive patients for malignancies." (PMID 30158896, 2018). "In addition, a patient has recently been described with motor symptoms such as apraxia, rigor, tremor, dysarthria, stimulus-sensitive myoclonic twitching of all limbs, mild cognitive impairment, and a verbal learning disability associated with anti-ARHGAP26 autoantibodies." (PMID 39081998, 2023). "Here, we observed predominant cognitive impairment in three ARHGAP26-positive patients - with in fact isolated cognitive deficits without other neurological symptoms in two of the patients." (PMID 30158896, 2018). "However, it is also possible that this is an epiphenomenon associated with anti-ARHGAP26 autoantibodies and that the patient's cognitive impairment is merely coincident with anti-ARHGAP26 autoantibodies and not caused by them." (PMID 39081998, 2023). "One possible explanation for cognitive deficits in ARHGAP26-positive patients is that autoantibodies not only bind to cerebellum, but also other brain structures such as limbic regions including the hippocampus." (PMID 30158896, 2018). "This issue can only be conclusively clarified in larger cohort studies of patients presenting with cognitive impairment with or without DLB, and with or without anti-ARHGAP26 autoantibodies." (PMID 39081998, 2023).
colorectal cancer (4 papers, 2019 to 2025). A primary or metastatic malignant neoplasm that affects the colon or rectum. "Loss of ARHGAP26 activity also dramatically increased the invasion of SW480 colorectal cancer cells." (PMID 31004081, 2019).
Autoimmunity (3 papers, 2010 to 2022). The occurrence of an immune reaction against the organism's own cells or tissues. "Our finding of high-titre anti-Ca/anti-ARHGAP26 antibodies in two additional patients with ACA strongly supports a role for autoimmunity against ARHGAP26 in the pathogenesis of this rare condition and proves that the index patient was not a singular case." (PMID 23320754, 2013). "Our finding of anti-Ca/anti-ARHGAP26 antibodies in two additional patients supports a role of autoimmunity against ARHGAP26 in the pathogenesis of ACA." (PMID 23320754, 2013). "Our findings expand the panel of diagnostic serum markers of autoimmune ataxia and suggest a role of ARHGAP26 autoimmunity in the pathogenesis of this condition." (PMID 20226058, 2010). "Our data suggest that additional autoimmunity to ARHGAP10 might contribute to the pathogenesis of neuroinflammation in a subgroup of ARHGAP26-IgG/anti-Ca-positive patients." (PMID 35624318, 2022). "Of note, however, ARHGAP10 is also expressed outside of the cerebellum, and autoimmunity to ARHGAP10 may thus explain the occurrence of extracerebellar symptoms in ARHGAP26-IgG/anti-Ca-positive patients." (PMID 35624318, 2022).